MSI1 (musashi RNA binding protein 1)
Diseases named in the same sentence as MSI1 in open-access papers (continued):
Sharing a sentence is not in itself a finding about the gene and the disease.
tumor (continued). "Hypoxia is the main challenge in early tumor growth and likely obscured any early growth differences as it may have affected Msi-1 knockdown and control tumors both." (PMID 35619161, 2022). "Focusing on cell proliferation and therapy resistance, we aimed to understand whether artificial Msi-1 knockdown may be a therapeutic venue to impede tumor growth and increase chemo- and radiosensitivity." (PMID 35619161, 2022). "MSI1 inhibition abrogates tumor initiation and significantly prolongs survival in both models." (PMID 36473869, 2022). "Msi-1 has been attributed radiosensitizing effects before in multiple tumor entities." (PMID 35619161, 2022). "This shows that in some cases, Msi-1 knockdown may have been able to halt tumor growth completely in early stages." (PMID 35619161, 2022). "All these studies indicate that MSI1 functions as a tumor promoter." (PMID 33882945, 2021). "Furthermore, MSI1 inhibits miR-671-5p suppression of TNF receptor-associated factor 2 (TRAF2) to induce CSC characteristics and tumor invasion and silence signal transducer and activator of transcription 3 (STAT3) to enhance radioresistance in GBM." (PMID 35052701, 2021). "The MSI1/ICAM1 pathway plays a vital role in tumor resistance, including increased tumor invasion." (PMID 35154340, 2021). "The disruption of MSI1/AGO2 interaction with decoy peptides efficiently inhibits tumor growth, suggesting that peptide-based therapy could be of importance to decrease recurrent GBM and PDAC." (PMID 31903115, 2020). "Concomitantly, in vivo studies showed that AGO2 knockdown abolished the MSI1-enhanced tumor growth." (PMID 31903115, 2020). "Both MSI1 translocation and MSI1/AGO2 binding are essential for promoting tumor progression." (PMID 31903115, 2020). "As MSI1 engages AGO2 to promote tumor progression through mRNA regulation, we asked whether the disruption of MSI1/AGO2 interaction could affect the tumor growth driven by cytosolic MSI1." (PMID 31903115, 2020). "Cytosolic MSI1 engages AGO2 to promote stress-induced tumor growth through RNA regulation." (PMID 31903115, 2020). "On the other hand, MSI1 expression is regulated by microRNAs in such a way that several different tumor suppressor miRNAs negatively regulate oncogenic MSI1 and inhibit migration and tumor metastasis." (PMID 32448364, 2020). "Whether MSI2 or MSI1, their expression levels in tumours are higher than those of corresponding normal tissues, and are related to tumour differentiation level, poor prognosis of patients, number of lymph node invasions and distant metastasis." (PMID 32606289, 2020). "In such anoikis-resistance analyses, MSI1 deletion severely impaired tumor cell vitality." (PMID 33291443, 2020). "Mice intracranially implanted with xenografts overexpressing MSI1-wt and sequentially treated with cisplatin showed an outrageous tumor invasion compared with other groups, suggesting that the nuclear-cytoplasmic shuttling of MSI1 strictly governs its biological function in tumorigenicity." (PMID 31903115, 2020). "Overexpression of MSI1 has been reported in several tumor tissues 9, 10, 13-17." (PMID 31903115, 2020). "Notably, overexpression of MSI1 C-terminus increased sensitivity to chemotherapeutic drugs, thus hindering the malignant progression of GBM, which opens the possibility to treat tumor recurrence via tackling the MSI1/AGO2 complex formation." (PMID 31903115, 2020). "miR-137 is a tumor suppressor, which negatively regulates MSI1 and Notch/WNT signaling pathway." (PMID 31440515, 2019).
tumor (continued). "Also DKK3, as one of the main targets for the post-transcriptional regulation of MSI1, functions as a tumor suppressor to block proliferation through interaction with LRP5/6." (PMID 30202417, 2018). "Moreover, there was a significant correlation between EGFR/MSI1 expression and grade of tumor differentiation (p = 0.02)." (PMID 30202417, 2018). "Therefore, simultaneous overexpression leads to moderate differentiation, whereas MSI1 overexpression stimulates the tumor into differentiation toward the well-differentiated state." (PMID 30202417, 2018). "Msi1 expression was higher in the tumor phase, but its expression level was very low." (PMID 28747693, 2017). "In a xenograft animal model, high expression ratio of MSI1 to TNS3 enhanced GBM tumor migration." (PMID 28821879, 2017). "In addition, the tumor cells in these xenografts exhibited strong staining for nuclear β-catenin and stem cell marker Musashi-1 (Msi-1)." (PMID 27302922, 2016). "Furthermore, knockdown of Msi1 lead to mitotic catastrophe in tumor cells and resulted in inhibition of Notch1, indicating that Msi1 regulates Notch signaling." (PMID 26270561, 2015). "Collectively the data supports our hypothesis that miR-137 acts as a tumor suppressor miRNA by down-regulating the oncogenic MSI1 that subsequently leads to tumor growth inhibition." (PMID 25940441, 2015). "Based on our preliminary data, we hypothesized that miR-137 acts as a tumor suppressor miRNA by negatively regulating MSI1." (PMID 25940441, 2015). "MSI1 was highly expressed in 79% of primary tumor samples, and 53% of metastatic lesion samples." (PMID 25940441, 2015). "All of these data indicate that Msi1 is highly expressed in human carcinogenesis and might function as a promoter in tumor development and progression." (PMID 25362645, 2014). "Furthermore, the down-regulation of Msi1 in HeLa and SiHa cells by shRNA inhibited the tumor formation in vivo and cell proliferation in vitro as well as in vivo." (PMID 25362645, 2014). "A total of 106 of the control and Msi1-modified HeLa and SiHa cells were subcutaneously inoculated into each posterior flank of the same female nude mouse(six mice per group) at the same time for the tumor formation assay." (PMID 25362645, 2014). "High expression levels of Msi1 were shown to be correlated with the grade of the malignancy in glioma, and primary central nervous system (CNS) tumors might share gene expression patterns with primitive, undifferentiated CNS cells." (PMID 25362645, 2014). "Msi1 is expressed not only in NS/PCs, but also in other somatic stem cells and in tumours." (PMID 21486496, 2011). "Msi1 KD reduces tumor cell survival and tumor xenograft growth, suggesting that it may represent a novel target for drug discovery." (PMID 20727204, 2010). "These tumour spheroid cells retain the expression of well-known cell surface markers, including CD133, CD166, CD44, and EpCAM, as well as other stem cell-associated proteins such as NES, BMI-1, and MSI-1." (PMID 20332776, 2010). "Msi1 KD in either cell line resulted in a 50-60% reduction in tumor growth." (PMID 20727204, 2010). "In this regard, Msi1 might be a positive regulator of tumor progression and a potential target for therapy." (PMID 18826648, 2008). "In this regard, Msi1 might be a positive regulator of tumor progression and a prospective target for therapeutic intervention." (PMID 18826648, 2008). "Therefore, STAT3 might maintain tumor growth after irradiation through MSI1-mediated attenuation of miR-671-5p." (PMID 35052701, 2021). "We demonstrated in vitro and in vivo that C-terminal terminus of MSI1 could work as a decoy to disrupt the endogenous MSI1/AGO2 interaction, and to efficiently block the oncogenic functions of the endogenous MSI1/AGO2 complex as well as inhibit xenograft tumor growth." (PMID 31903115, 2020). "Therefore, MSI1/AGO2 pathway promotes stress-induced tumor growth." (PMID 32448364, 2020).
tumor (continued). "Besides that, the expression level of proteins which are utilized by ZIKV for viral entry and replication such as AXL and MSI1 in tumor cells may affect the efficacy of the OV therapy." (PMID 31824472, 2019). "Furthermore, miR-93 and MSI1 mediated the tumor suppression of LOCCS knockdown." (PMID 29110645, 2017). "In addition, a tumor-growth assay in vivo using NOD-SCID mice demonstrated that xenografts expressing MSI1-KD resulted in a smaller tumor size (as seen by a marked decrease in BLI) and longer mouse survival compared with their counterparts treated with control shRNA-expressing xenografts." (PMID 22428049, 2012). "FMRP interacts with both GSK3β and CTNNB1, MSI1 represses APC and enhances Wnt signaling in epithelial progenitors, while MEX3A stabilizes LGR5 and represses DKK1, thereby promoting stemness and tumor progression." (PMID 41516083, 2025). "Together, our data suggest MSI1 is a regulator of human NSC and is required for tumor propagation in human G3 MB." (PMID 36473869, 2022). "Instead, we employ a multi-platform approach to identify differentially binding targets of MSI1 in G3 MB and NSC, elucidating tumor-specific targets for future therapeutic design." (PMID 36473869, 2022). "The expression of TWIST1, CRIPTO1, SOX2, and MSI1 were evaluated in ESCC patients, indicating their role in tumorigenesis and tumor cell aggressiveness." (PMID 36553636, 2022). "This mimicking ability of Pep#11 and Pep#26 resulted in interference to endogenous MSI1/AGO2 interaction, thereby impairing cellular survival and tumor progression in GMB and PDAC animal models." (PMID 35158774, 2022). "Overexpression of the C-terminus of MSI1 disrupts endogenous MSI1/AGO2 interaction and effectively reduces stress-induced tumor progression." (PMID 35158774, 2022). "As a result, Pep#11 and Pep#26 were identified in the arrays and were demonstrated to be effective in not only the MSI1/AGO2 complex disruption in vitro, but in vivo as well where the tumor suppression capability was delineated." (PMID 35158774, 2022). "Compared with A375 cells, A375 xenograft tumor displayed an upregulation for glial and neuronal genes (GFAP, BDNF, MAP2, MTURN, ROBO2, SYT1 and TUBB3) and neural stemness genes (ASCL1, MSI1, PAX6, PDGFRA, SOX9, VIM, ZIC1/2)." (PMID 33468253, 2021). "MGO-induced carbonyl stress can also enhance the degree of malignancy of tumor cells and increased the expression of tumor proliferation and migration markers CD29, CD44, and Msi-1." (PMID 34947850, 2021). "Collectively, our findings identified a novel role of MSI1 in the secretion of MIF1 and the consequent polarization of macrophages into the M2 phenotype in promoting GBM tumor progression." (PMID 33918794, 2021). "The study found that MSI1 as a stem gene in colorectal cancer cells is a key regulator of CD44+ CSC development and enhances tumor stem cell therapy resistance by triggering the formation of anti-apoptotic stress granules (SGs)." (PMID 33588867, 2021). "Xenograft tumor of HCT 116 showed an increased expression of neuronal genes MAP2 and SYN1, neural stemness genes CDH2, MSI1, NCAM1, SOX2/9, VIM and ZEB2, and genes for mesodermal and endodermal tissues (ACP5, AFP, DESMIN, HNF4A and KRT8)." (PMID 33468253, 2021). "These lead compounds proved suitable in cellulo and in vivo to impair oncoRBP function, as demonstrated here by the inhibition of MSI1-enhanced CD44 expression and induction of tumor cell differentiation by the MSI1 inhibitor luteolin." (PMID 33291443, 2020). "MSI1 and MSI2 are highly expressed in various tumours such as glioma, breast cancer, pancreatic cancer, colon cancer, lung cancer, ovarian cancer and prostate cancer." (PMID 32606289, 2020). "REXO2, MSI1, and ESRP2 had high expression levels in tumors compared with normal tissues, while CTU1, MAEL, and YBX2 were undetermined in both tumor and normal tissues." (PMID 33193734, 2020).
tumor (continued). "Evidently, overexpression of MSI1 has been observed in several types of tumors, including GBM, and is regarded as a well-established marker for tumor metastasis and recurrence." (PMID 31824472, 2019). "Notch1+ tumour cells (GFP+) also showed enriched expression in reported markers of ISCs, such as Hopx2, Musashi122 (Msi1) and Bmi17 compared to GFP-epithelial cells within the same tumours." (PMID 30696875, 2019). "In contrast, there was a reverse correlation between MSI1/EGFR expression and tumor depth of invasion, in which MSI1 is involved in T3 depth of invasion, whereas the EGFR is involved in T2 depth of invasion." (PMID 30202417, 2018). "In the case of tumor size, the biggest and smallest tumors were observed among patients with EGFR underexpression or MSI1 overexpression and patients with EGFR/MSI1 overexpression, respectively (5.67 ± 3.18 and 3.5 ± 0.58 cm)." (PMID 30202417, 2018). "We also confirmed that MSI1 and TNS3 expressions are mutually exclusive in migratory tumor lesions, and GBM patients with MSI1high/TNS3low pattern tend to have poor clinical outcome." (PMID 28821879, 2017). "MSI1 regulates NUMB translational inhibition to restrict proteasome activity and preserve the tumor initiating ability of breast and GBM cells." (PMID 28821879, 2017). "Our work reveals a novel mechanism for MSI1 dysregulation in CRC and demonstrates miR-137 as a tumor suppressor miRNA." (PMID 25940441, 2015). "Based on these premises, in order to characterize the expression of putative stem markers during the early phases of carcinogenesis, we studied the expression of LGR-5, MSI-1, DCAMKL-1, CD133 and ALDH1-A1 in both MDF and tumours by immunohistochemistry." (PMID 23374535, 2013). "On the contrary, genes of other proposed stem cell markers, such as Dcamkl-1, Msi-1 and Prom-1 (CD133), were down-regulated in DMH-tumours." (PMID 23374535, 2013). "Immunofluorescent staining identified ∼30–40% of tumour spheroid cells expressing NES, BMI-1, and MSI-1." (PMID 20332776, 2010). "Another study reported that the interaction of eIF2 with Musashi1 (MSI1), an RNA-binding oncoprotein that controls the balance between self-renewal and differentiation during neurogenesis, promoted tumor chemoresistance in GB cells." (PMID 36994107, 2023). "Although not highly specific at present, a number of novel MSI1–directed inhibitors already show promising anti–tumor potential." (PMID 34062997, 2021). "MSI1 may regulate GBM radioresistance, CSCs and tumor motility through miR-671-5p inhibition to increasing STAT3 and TRAF2 presentation." (PMID 35052701, 2021). "Furthermore, GBM tumor model data suggested that the tumor growth, MIF1 expression and M2 macrophage population were significantly downregulated when MSI1 expression was silenced in vivo." (PMID 33918794, 2021). "Collectively, our results indicated that the cytosolic MSI1/AGO2 complex interaction and downstream pathway was significantly enhanced in patients with tumor relapse and could affect patient survival." (PMID 31903115, 2020). "Importantly, the MSI1 mRNA abundance remains high in recurrent GBM, suggesting a fundamental role of MSI1 in CSC maintenance and tumor recurrence." (PMID 33291443, 2020). "Some studies identify both MSI-1 and MSI-2 as potential therapeutic targets: MSI-1 has been described to enhance BCSC characteristics through proteasome subunit expression regulation, and anti-tumor effects subsequent to MSI-2 targeting have been shown in breast cancer." (PMID 32245259, 2020). "Thus, our findings reveal an undescribed mechanism by which MSI1 promotes tumor cell stemness and highlight the pivotal role of oncofetal RBPs like IGF2BP1 and MSI1 in promoting a stem-like tumor cell phenotype by antagonizing miRNA-dependent regulation." (PMID 33291443, 2020). "Importantly, overexpression of the C-terminus of MSI1 disrupts endogenous MSI1/AGO2 interaction and effectively reduces stress-induced tumor progression." (PMID 31903115, 2020).
tumor (continued). "Herein, we evaluate the neurotropism of ZIKV relative to the receptor tyrosine kinase AXL and its ligand Gas6 in viral entry and the RNA-binding protein Musashi-1 (MSI1) in replication which are also overexpressed in GBM, suggesting its potential for specific targeting of the tumor." (PMID 31824472, 2019). "For example, we found that E-cadherin, ESRP1 staining was greatly increased in tumors from CDX2;APC;PID mice, whereas Msi1 was decreased in these tissues, relative to tumor tissue from animals lacking PID expression." (PMID 30150766, 2018). "In this study, we revealed MSI1 plays an important role in AKT activation and IL-6 secretion in response to chemo-drug in GBM cells, which eventually contributes to a dynamic interaction between proinflammatory circuits, chemoresistance, and tumor recurrence." (PMID 27285760, 2016). "Overall, we describe an important tumor-suppressive mechanism of miR-137 through the negative regulation of MSI1 and Notch/Wnt signaling, outlined in our working model." (PMID 25940441, 2015). "Msi1, ALDH1, and Sox2 expression were positively correlated with tumor recurrence (P = 0.005, P = 0.003, and P = 0.003, respectively), while CD49f expression was negatively correlated with tumor recurrence (P = 0.028)." (PMID 26499463, 2015). "Similarly, the SiHa-Msi1 cells formed a tumor much faster (a palpable tumor took 23 days for SiHa-Msi1 cells and 29 days for SiHa-EGFP cells), and the tumor was larger (P<0.05) and heavier (P<0.05) than with the SiHa-EGFP control cells." (PMID 25362645, 2014). "Msi1 was enriched in CD133+ MCF-7 and T47D cells, particularly when grown as spheroid cultures, and Msi1 'knockdown' reduced spheroid colony formation and tumor xenograft growth." (PMID 20727204, 2010). "In contrast, we observed the opposite effect in MSI1- and AGO2-knockdown cells, suggesting that MSI1/AGO2 complex could stabilize in response to stress a subset of mRNA targets related to cell cycle (group 1) to subsequently promote tumor progression." (PMID 31903115, 2020). "Taken together, our study indicates the autonomous MSI1-dependent regulation of AKT and IL-6 in GBM, and partly answered the unsolved question of how MSI1 takes effect on autocrine/paracrine secretion, as well as tumor environmental pro-inflammatory biogenesis." (PMID 27285760, 2016). "Moreover, the negligible MSI1 expression in most adult tissues and the presence of antiviral defense responses, such as IFN which restricts virus replication in normal cells, suggest high specificity of ZIKV infection toward the tumor with limiting side effect in patients." (PMID 31824472, 2019). "In esophagus cancer, MSI1 expression is the highest in glandular structure during early cancer development, but it becomes weaker when adenocarcinoma progresses to the advanced stage, suggesting that MSI could be a marker of CSC during an early phase of tumor development." (PMID 29064439, 2017). "Based on our in vitro and in vivo findings, we propose that tumor stem cells treated with MSI1-KD lose their self-renewal ability and undergo a non-apoptotic programmed cell death, which may explain the difference in tumor growth between the control and MSI1-KD groups." (PMID 22428049, 2012). "Immunoprecipitation of MSI1 and AGO2 from the orthotropic xenograft tumor tissue confirmed the interaction between MSI1 and AOG2 in the MSI1-wt but not MSI1-NES-mut and MSI1-NLS-mut tumors." (PMID 31903115, 2020). "Based on its prevalent localization at the base of normal crypts, as expected for stem cells, and on the overexpression in precancerous lesions and tumours, we support LGR-5, but not MSI-1 or DCAMKL-1, as putative neoplastic stem cell marker." (PMID 23374535, 2013). "Analysis of the effect of Msi1 expression on survival time with or without adjustment for age, TNM stage, tumor grade, and tumor size in the Cox regression model indicated that the hazard role of Msi1 was significant." (PMID 20727204, 2010).
tumor (continued). "In vitro, the absence of the tumor microenvironment in our MCF-7 cell culture may have acted as a confounder (and even the MCF-7 data showed a strong decrease in cell viability through MSI-1 knockdown alone)." (PMID 34291358, 2021).